GAB4 (GRB2 associated binding protein family member 4)
Tractability: No criterion of Open Targets' tractability assessment is met for any kind of drug.
Gene: Protein-coding gene on chromosome 22 (16,961,936 to 17,008,222, reverse strand). Ensembl gene ENSG00000215568.
Gene Ontology:
Molecular function: transmembrane receptor protein tyrosine kinase adaptor activity
Biological process: signal transduction; cell surface receptor protein tyrosine kinase signaling pathway
Cellular component: cytoplasm
Genetic constraint (gnomAD): Loss-of-function variants: 26 observed, 49.38 expected, observed/expected ratio (o/e) 0.53, 90% interval 0.38 to 0.73. The upper end of that interval is the gene's LOEUF score, 0.73, which puts it in group 2 of 6, group 1 being the genes least tolerant of losing a copy. Missense variants: 758 observed, 760.8 expected, observed/expected ratio (o/e) 1, 90% interval 0.94 to 1.06. Synonymous variants: 329 observed, 304.09 expected, observed/expected ratio (o/e) 1.08, 90% interval 0.99 to 1.18.
Homologues: Orthologues: chimpanzee GAB4 (97% identical), macaque GAB4 (81% identical), Drosophila melanogaster dos (19% identical), Caenorhabditis elegans soc-1 (12% identical). Paralogues in human: GAB2 (59% identical), GAB1 (30% identical), GAB3 (26% identical), PHLDB1 (17% identical), PHLDB2 (12% identical), PLEKHS1 (11% identical), PHLDB3 (7% identical).
Diseases named in the same sentence as GAB4 in open-access papers:
GAB4 is named in the same sentence as 4 diseases in open-access papers, as found by Europe PMC text mining. Sharing a sentence is not in itself a finding about the gene and the disease. The quoted sentences say what the papers report.
hypoglycaemia (1 paper, 2014). "We can hypothesize that gene dosage alterations of GAB4 and ADA2 and their possible functional interactions could be subject of changes in carbohydrate metabolism and these are likely the cause of hypoglycaemia susceptibility of the presented patient." (PMID 24959203, 2014).
infection (1 paper, 2012). The state of being infected such as from the introduction of a foreign agent such as serum, vaccine, antigenic substance or organism. "SIVcpzPtt-Gab4 infection was associated with neither T-cells proliferation nor T-cells activation." (PMID 22984489, 2012).
GAB4 also shares sentences with these, for which no sentence is quoted: cat-eye syndrome (1 paper); resistant hypertension (1).